DKK1 (dickkopf Wnt signaling pathway inhibitor 1)
Diseases named in the same sentence as DKK1 in open-access papers (continued):
Sharing a sentence is not in itself a finding about the gene and the disease.
tumor (continued). "RNA-seq analysis performed on osteocytes isolated from non-tumor bearing mice revealed that these cells expressed Sost, Dkk1 and other Wnt antagonist such as Sfrp1, Sfrp2 and frizzled-b (Frzb)." (PMID 30410490, 2018). "DKK1 is expressed in a variety of tumor types and elevated levels frequently correlate with poor survival." (PMID 30400822, 2018). "We found that immunized mice with including DKK1 vaccine groups were longer median survival and was slower tumor growth than that of control groups (NS, vector, hHSP70 groups)." (PMID 29416605, 2018). "Surprisingly few co-culture experiments have been performed focusing on the interaction of Dkk-1 expressing tumors and osteoprogenitors even though the presence of stroma can profoundly affect proliferation and viability of tumor cells." (PMID 30478297, 2018). "To evaluate the clinical utility of serum DKK1 as a bone metastasis biomarker, we also measured the conventional tumor marker CEA in patients with stage IV." (PMID 29108326, 2017). "These phenomena can indicate the DKK-1-mediated promotion of cancer growth by activation of tumor angiogenesis and support the rationale that DKK-1 can be a cancer-specific therapeutic target for HCC treatments." (PMID 28938611, 2017). "The authors showed that anti-DKK1 treatment increased β-catenin expression in myeloid-derived suppressor cells and suggested that attenuating DKK1 activity by neutralization recruited T cells to the tumor site and decreased tumor growth." (PMID 28178355, 2017). "Dickkopf-1 (DKK-1), an antagonist of Wnt signaling, participates in tumor development and progression." (PMID 28938611, 2017). "DKK1 is a negative regulator of the Wnt/β-catenin pathway in multiple tumor types and has been classified as a tumor suppressor for this role." (PMID 28388562, 2017). "It has been reported that the expression of DKK1 were downregulated, resulted in β-catenin degradation and retardation of proliferation of tumor cells." (PMID 27608843, 2016). "Significant levels of human DKK-1 (ranging from 500 to 2200 pg/ml) were detected in the serum of tumor-bearing mice over the first 4 weeks, but surprisingly levels fell to nearly undetectable as tumors grew larger." (PMID 27049730, 2016). "Serum DKK-1 levels were monitored weekly and leg circumference was measured weekly to monitor tumor growth." (PMID 27049730, 2016). "The lowered DKK‐1 autoantibody levels were also detected in most serum samples from patients who had undergone tumor resection—a finding indicating that the DKK‐1 autoantibody is attenuated on removal of the “immunogen”." (PMID 26988995, 2016). "Studies in paediatric patients with OS showed significantly elevated levels of DKK1 in serum of patients with maximal DKK1 expression detected in tumour cells and tumour-surrounding cells." (PMID 27367730, 2016). "Most importantly, implantation of DKK1-shRNA HCCA cells into nude mice impaired their tumor formation capacity in vivo." (PMID 27608843, 2016). "We were able to detect human DKK-1 in the blood of tumor-bearing mice and found a correlation between DKK-1 level and tumor proliferation." (PMID 27049730, 2016). "In the 116 GC patients, the DKK1 level inversely correlated with clinical parameters, such as tumor class, TNM stage, distant metastasis and lymph node metastasis, but not the histological grade." (PMID 26799283, 2016). "During the late phase, when control animals had undetectable serum DKK-1, tumor growth velocity was unaffected by treatment with BHQ880." (PMID 27049730, 2016). "DKK1 expression was negatively related with clinical parameters, such as tumor class, TNM stage, distant metastasis and lymph node metastasis, but positively related with prognosis." (PMID 26799283, 2016). "Based on our characterization of human primary tumours, the expression of CSC‐related proteins that were significantly associated with VM and DKK1 were examined." (PMID 27240974, 2016).
tumor (continued). "As shown, tumors derived from DKK1 overexpressing SGC-7901 cells had a significantly reduced tumor size compared with related control cells." (PMID 26799283, 2016). "Other studies also showed elevated levels of DKK1 in patients’ sera or tumour specimen from a squamous cell carcinoma of the head and neck (SCCHN), including esophageal and laryngeal tissues." (PMID 27367730, 2016). "Positive staining of DKK1 protein by immunohistochemistry was observed in the cytoplasm of tumor cells." (PMID 27608843, 2016). "Immuno-histochemistry revealed that DKK1 expression was positively correlated with subcutaneous tumor volume." (PMID 27608843, 2016). "Summary, we here demonstrated that DKK1 acted as a tumor suppressor in GC, and its expression level was correlated with GC prognosis." (PMID 26799283, 2016). "The DKK‐1 levels after tumor resection dropped below cutoff value in nine of 10 patients, and the levels of DKK‐1 autoantibody also decreased below the cutoff line in five of seven ESCC patients after treatment." (PMID 26988995, 2016). "In general, high DKK1 expression (++ or +++) was observed in 24 of 37 tumor samples (64.9%), whereas low DKK1 expression (− or +) was noted in 13 of 37 tumor samples (35.1%)." (PMID 27608843, 2016). "In vivo animal studies demonstrated that DKK1 enhances the growth of transplanted human tumours cells, as well as increased VM formation, mesenthymal phenotypes and CSC properties." (PMID 27240974, 2016). "These potential protective effects contrast with the overexpression of DKK-1 in several types of cancer associated with a poor prognosis, and make the role of DKK-1 as tumor suppressor or metastasis promoter a matter of debate." (PMID 25788273, 2015). "The largest number of participants in this study was in the PC patient group which enabled correlative analysis of DKK1 expression in PC tumor tissues and serological DKK1 levels." (PMID 26101916, 2015). "Despite some conflicting reports about DKK-1 promoting migration and invasion, it is recognized as a tumor suppressor and an inhibitor of Wnt signaling." (PMID 26646695, 2015). "DKK1-expressing tumours are bigger with higher vascular density and little attachment of VSMCs/PCs to ECs." (PMID 25311137, 2015). "In summary, these data indicate that knockdown of DKK1 also can sensitize cells of other tumor types than NSCLC to cisplatin." (PMID 26353782, 2015). "Taken together, these results indicate that the tumor suppressive action of DKK-1 in DLD-1 cells in which the Wnt/β-catenin pathway is endogenously activated due to APC mutation is independent of Wnt." (PMID 25788273, 2015). "The role of MSC signaling through Wnt in cancer progression has been reported in previous publications, despite an inhibitory effect on tumor growth was reported in a study using Z3-MSCs, a cell line producing Dkk-1, an inhibitor of Wnt/β-catenin signaling." (PMID 26060426, 2015). "IPA analysis identified p21WAF1/Cip1 to be a putative downstream effector protein of DKK1, and p21WAF1/Cip1 is reported to negatively regulate the cell cycle, i.e. to have a tumor suppressor role." (PMID 26353782, 2015). "Intratumoral Ad-DKK1 injection into standard-sized tumors (approximately 100 mm3) significantly retarded tumor growth compared to Ad-Mock control construct-infected tumors [874 ± 162 vs. 2,277 ± 186 mm3, over 13 days of growth (p < 0.001)]." (PMID 24091497, 2014). "We analyzed tumor vessel density of Ad-DKK1- and Ad-DKK2-transfected tumors, in comparison with Ad-Mock transfectants." (PMID 24091497, 2014). "The biological functions of DKK-1 in the bone metastatic process and in tumor progression suggest its potential therapeutic role as a target." (PMID 24655661, 2014). "Previous reports have demonstrated that DKK1 can suppress the Wnt-induced signaling that is frequently activated in tumor biology." (PMID 25144498, 2014).
tumor (continued). "The expression of Wnt pathway components was similar in tumor tissue/initial cultures, melanospheres and monolayers, except for DKK1." (PMID 24733089, 2014). "Some of the mRNAs stabilized by RBM47, as exemplified by dickkopf WNT signaling pathway inhibitor 1, inhibit tumor progression downstream of RBM47." (PMID 24898756, 2014). "In certain tumor cells, the epigenetic silencing of Dkk-1 by promoter hypermethylation contributes to aberrant Wnt/β-catenin signaling." (PMID 24747916, 2014). "Although additional work is required to clarify the effects of DKK1 on tumor angiogenesis, our results consistently support that Wnt regulates tumor angiogenesis." (PMID 24091497, 2014). "Tumor angiogenesis, as measured by microvascular density, was decreased in DKK1 Tg mice to levels 68 % of those seen in control animals, whereas vessel density in DKK2 Tg mice was increased to levels 127 % of those seen in wild-type animals." (PMID 24091497, 2014). "In line with this, inhibition of DKK1 expression in the MDA231-BrM2 cells promoted tumor formation in the orthotopic site." (PMID 24898756, 2014). "One of the genes significantly up-regulated by linc00467 siRNA-1 was DKK1, a Wnt antagonist tumour suppressor gene known to induce cancer cell apoptosis." (PMID 24586304, 2014). "Our findings suggest that DKK1 decreases B16F10 tumor growth through regulating the tumor vasculature." (PMID 24091497, 2014). "To confirm the effect of DKK1 and DKK2 on tumor angiogenesis, we used DKK1 Tg and DKK2 Tg mice that we generated for our previous study." (PMID 24091497, 2014). "In this study, the role of DKK1 in tumor cell proliferation, migration and invasion was investigated using MTT, colony formation, wound scratch, transwell assays, and also human HCC samples." (PMID 24325363, 2013). "Although the members of the DKK family normally act as secreted Wnt antagonists and therefore should suppress Wnt-induced tumor growth, DKK1 has been shown to be overexpressed in HCC tumor tissues." (PMID 23776502, 2013). "In the present study, EC cells transfected with DKK1 siRNA showed increased tumor cell invasion and migration when compared with the untreated and control-treated cells, indicating an upregulation of β-catenin and MMP14." (PMID 24137406, 2013). "The results of the current study are consistent to that of previous studies reporting the involvement of the knockdown of DKK1 in tumor cell invasion and migration." (PMID 24137406, 2013). "Four out of six neoplasias were found in the mice showing higher methylation at CGIs of all five genes Dkk1, Slc5a8, Hoxd1, Socs1 and Sfrp1 (B219, B220), of the four genes Dkk1, Hoxd1, Socs1 and Sfrp1 (B215), or of Dkk1 (B236)." (PMID 24204690, 2013). "Taken together, all these findings suggest that DKK1 performs an oncogenic or a tumor-suppressing function depends on the cell type or context." (PMID 24325363, 2013). "Of these, 46 (45.1%) showed strong positive DKK1 expression, mainly in the cytoplasm of tumor cells, with dark brown granular distribution." (PMID 24391982, 2013). "Here, our data clearly suggested that DKK1 can directly promote tumor cell migration and invasion by stimulating β-catenin transcription and translation through a non-canonical Wnt signaling pathway in HCC cells." (PMID 24325363, 2013). "Dkk1 drew our particular attention, since 4 out of the 6 neoplasms were found in mice which showed Dkk1 inactivation." (PMID 24204690, 2013). "Consistently, in human HCC tissues, DKK1 level was positively correlated with β-catenin expression, as well as tumor metastasis." (PMID 24325363, 2013). "Several studies have shown that DKK1 can either inhibit or promote tumor progression and metastasis." (PMID 24325363, 2013). "In mice fed with WD, proximal colon mucosa, the predominant site of cancer formation in LS, exhibited a significant expression decrease in tumor suppressor genes, Dkk1, Hoxd1, Slc5a8, and Socs1, the latter two only in the Mlh1+/- mice." (PMID 24204690, 2013).
tumor (continued). "Intriguingly, up-regulation of DKK1 significantly promoted HCC cell migration and invasion, vice versa, when DKK1 is repressed by a DKK1-specific shRNA, the tumor cell migration and invasion is markedly reduced." (PMID 24325363, 2013). "The RNAi-mediated targeting of DKK1 gene expression in Ishikawa EC cells resulted in increased tumor cell invasion and migration." (PMID 24137406, 2013). "Previously, we reported that DKK-1 counteracts tumor cell invasion induced by coculture with whole MΦ." (PMID 24185202, 2013). "We further tested the prognostic value of DKK1 in different tumor stage or lymph node status subgroups." (PMID 22649545, 2012). "Consistent with a tumor suppressor function, DKK1 silencing during tumor progression has been reported in several types of cancer." (PMID 22363428, 2012). "As for overall survival, tumor stage, DKK1 and beta-catenin were found to have significant prognostic values while no such correlation was found in other factors." (PMID 22649545, 2012). "Our finding that ectopic expression of PRDM5 leads to the inhibition of WNT/β-catenin signaling in tumor cells, probably through upregulating DKK1, DKK2, and WNT5A, suggests a novel mechanistic link between PRDM5 and WNT signaling in human tumorigenesis." (PMID 22087297, 2011). "We subsequently confirmed by means of semiquantitative RT-PCR experiment overexpression of DKK-1 mRNA in 26 tumor tissues frozen in liquid nitrogen, but its transcript was hardly detectable in any other normal tissues (P < 0.05)." (PMID 21029453, 2010). "DKK-1 also inhibits epithelial cell polarization and migration, processes that are important in tumor progression and metastasis." (PMID 21317455, 2010). "To evaluate the clinical usefulness of cerebral flucid DKK-1 level as a tumor detection biomarker, we also measured by ELISA the levels of DKK-1 protein in cerebral flucid samples from the same set of tumor patients and control individuals." (PMID 21029453, 2010). "The results of this study support our previous findings, and those of others, that increased bone mass resulting from exogenous MSC cytotherapy or treatment with DKK1-neutralizing antibody, Wnt3a, or lithium chloride negatively impact MM tumor burden in bone." (PMID 21188144, 2010). "Hyper-methylation of the promoter and gene silencing of DKK1 were observed in tumor cells, including colorectal cancer and malignant melanoma cells." (PMID 19247449, 2009). "An inverse relation of ASCL1 to DKK1 protein expression was observed for 15 out of 22 tumours (68%)." (PMID 19744316, 2009). "An inverse relation of ASCL1 to DKK1 expression was observed in 68% of the analysed tumours (n = 22)." (PMID 19744316, 2009). "The suppression of DKK1 expression has been observed in several tumors, and although elevated level of the DKK family occur in a number of tumor cells, most reports to date have been concerned with DKK1 and DKK3." (PMID 19247449, 2009). "We also observed methylation of DKK1, although less frequently, in cell lines (3 out of 11, 27%) and primary tumours (15 out of 78, 19%)." (PMID 18283316, 2008). "By Real-Time PCR, we quantified DKK-1 and IL-7 gene expression on micro-dissected tumour and healthy tissue sections." (PMID 18978943, 2008). "Recent data reported DKK-1 expression in some human specimens of tumours, suggesting that a cancer-mediated modulation of WNT activity influences the metastatic phenotype." (PMID 18978943, 2008). "In bone, expressions of MCSF and DKK1 were shown in stromal cells of the bone marrow, in contact with metastatic foci of both tumours." (PMID 18253114, 2008). "Precisely, in DKK1+ tumours, the mRNA level was significantly higher in ER−/PR− compared to other tumours (respectively 818 vs 213 DKK1 mRNA copies/105β-actin copies, P=0.009)." (PMID 17245340, 2007). "We describe here DKK1 expression in human tumours of various origins, including breasts, lungs and kidneys." (PMID 17245340, 2007).
tumor (continued). "The presence of high levels of Dkk-1 and RANKL facilitate expansion by allowing the proliferative cells at the periphery of the tumour to accelerate bone resorption through expression of RANKL while inhibiting osteoid repair through the action of Dkk-1." (PMID 17987039, 2007). "We also found that Dkk-1 was maximally expressed by the OS cells at the tumour periphery and in vitro, Dkk-1 and RANKL are coexpressed by rapidly proliferating OS cells." (PMID 17987039, 2007). "Smaller spheroids expressed Dkk-1 throughout, but the larger structures adopted an expression pattern for Dkk-1 that mimicked the tumour biopsies with the maximal level of expression at the periphery." (PMID 17987039, 2007). "In instances of osteolytic tumours, the presence of Dkk-1 would be predicted to exacerbate lesion formation through inhibition of Wnt-dependent osteogenesis." (PMID 17987039, 2007). "In mice, we found that the expression of Dkk-1 from implanted tumours was similar to the human tumour biopsies in that human Dkk-1 was present in the serum of recipient animals." (PMID 17987039, 2007). "The correlation of tumour load with Dkk-1 levels also suggests that the assay also has potential for measuring the relative size and severity of such tumours." (PMID 17987039, 2007). "Previous studies have shown that artificial DKK1 expression in some tumour lines with constitutive activation of the β-catenin pathways resulted in some decrease of cell viability but only in the presence of an oxidative stress inducer." (PMID 17245340, 2007). "Immunohistochemical staining of excised tumour biopsies demonstrated that Dkk-1 was expressed maximally at the periphery of the tumour, adjacent to the hosts' bone tissue." (PMID 17987039, 2007). "Reducing the osteoinhibitory effects of Dkk-1 would therefore be predicted to reduce local bone damage, and as a result, probably reduce the expansion of the tumour." (PMID 17987039, 2007). "Upon histological examination of serial sections of excised tumour tissue, the areas that stained most intensely for Dkk-1 were accompanied by extensive remodelling." (PMID 17987039, 2007). "All tumours from patients with stage IIIC were DKK1+ (P=0.04), which includes tumours of any size presenting 10 or more metastatic axillary nodes." (PMID 17245340, 2007). "In vivo, DIC inhibits tumor growth, an effect partly mediated through the DKK1/β-catenin axis." (PMID 41827705, 2026). "Furthermore, DKK1 serves as a critical orchestrator of the tumor microenvironment (TME) by driving comprehensive immune reprogramming." (PMID 42123366, 2026). "DKK1 was reported to favor tumor growth and metastatic state in EAC." (PMID 39795613, 2025). "Wnt signalling inhibitor DKK1 Promotes tumor immune evasion and impedes Anti-PD-1 treatment." (PMID 40302814, 2025). "To better understand how DKK1 promotes tumor progression in vivo, we performed bulk RNA sequencing using GFP-H2B-mApple-Thy1.1+ PyMT-BO1 cells isolated from orthotopic tumors in WT mice receiving IgG or mDKN01, after exclusion of Ter119+ erythrocytes and CD45+ immune cells." (PMID 39885132, 2025). "The Wnt/β‐catenin pathway can be inhibited by Dickkopf‐1 (DKK1), which also promotes tumor growth." (PMID 40475985, 2025). "Because αSMA is also expressed in myoepithelial and endothelial cells, to further determine the relevance of CAF-derived DKK1 during tumor progression, as a complementary approach we crossed Dkk1fl/fl mice with the FSP1 Cre line (referred to as FSP1-Dkk1cKO) to allow deletion of Dkk1 in fibroblasts." (PMID 39885132, 2025). "Furthermore, the growth of MDA-MB-231 tumor cells, which display nuclear DKK1 localization, is reduced when these cells are co-injected with Dkk1-deficient CAFs compared to Dkk1-sufficient CAFs." (PMID 39885132, 2025). "To assess whether DKK1 exerts direct effects on tumor cell proliferation, we cultured the PyMT, 4T1, and E0771 tumor cells in the presence of recombinant DKK1 (rDKK1) and performed an MTT assay." (PMID 39885132, 2025).